RN7SKP243 (RN7SK pseudogene 243)
Gene: Miscellaneous RNA gene on chromosome 11 (73,832,382 to 73,832,690, reverse strand). Ensembl gene ENSG00000199975.
Homologues: Orthologues: chimpanzee 7SK (97% identical), guinea pig 7SK (64% identical), mouse Gm54535 (49% identical). Paralogues in human: RN7SKP176 (78% identical), RN7SKP180 (77% identical), RN7SKP9 (77% identical), RN7SKP255 (77% identical), 7SK (76% identical), RN7SKP203 (76% identical), RN7SKP37 (76% identical), RN7SKP47 (76% identical), RN7SKP133 (75% identical), RN7SKP45 (75% identical), RN7SKP189 (75% identical), RN7SKP211 (75% identical), and 284 more.